IL6 (interleukin 6)
Diseases named in the same sentence as IL6 in open-access papers (continued):
Sharing a sentence is not in itself a finding about the gene and the disease.
lung carcinoma (continued). "IL-6 can be detected in breath condensate of patients with non-small cell lung cancer (NSCLC), and in serum of some lung cancer patients, but is not detectable in patients with benign lung disease." (PMID 24260500, 2013). "Despite existing evidence supporting the functional link between TGF-β1 and IL-6 in various human diseases, the study found no elevated concentrations of IL-6 in BALF for lung cancer patients, although a significant correlation between TGF-β1 and IL-6 in BALF was observed." (PMID 37373987, 2023). "IL-6 was decreased in both of the erlotinib-sensitive EGFR-mutant lung cancer cell lines (HCC4006 and HCC827) and was not changed in the erlotinib-resistant EGFR-mutant lung cancer line (H1975) after erlotinib treatment." (PMID 36612121, 2022). "The activities of SP‐1 and STAT3 induced by NF‐κB, USF1, and IL‐6 were not significantly affected by K284 treatment, but lipopolysaccharide‐ and TNF‐α‐induced SP‐1, STAT3, and AP‐1 were significantly decreased by K284 treatment in A549 lung cancer cells." (PMID 34758182, 2022). "After the knockdown of MRE11 in lung cancer cells, we discovered that IL-6 or the conditional medium of THP-1 cells can induce the mRNA expression of STAT3 downstream genes, including CCL2, in the control cells, but not in MRE11-knockdown lung cancer cells." (PMID 36547079, 2022). "Interestingly, S1P-induced IL-6, but not TNF-α, release from lung cancer-derived PBMCs was mTOR- and K-Ras-dependent, while NF-κB was not involved." (PMID 36010601, 2022). "After 6 h with HHT treatment, IL-6-induced STAT3 phosphorylation in A549 and H1975 cells almost recovered which indicated that the HHT inhibition on STAT3 phosphorylation in lung cancer was reversible and the recovery was not due to new synthesized STAT3 protein by CHX-treatment experiment." (PMID 26166037, 2015).
psoriasis (753 papers, 2006 to 2026). An autoimmune condition characterized by red, well-delineated plaques with silvery scales that are usually on the extensor surfaces and scalp. "contains bioactive flavonoids and alkaloids that exert anti-inflammatory and antioxidant activities, and inhibit TNF-α, IL-1β, IL-6 and NF-κB signaling pathways implicated in the pathogenesis of psoriasis." (PMID 42306466, 2026). "Both IFN-γ and TNF-α are known to induce the expression of IL-6, IL-8, IL-12, and IL-18, thereby constituting a key regulatory axis within the cytokine network implicated in psoriasis." (PMID 40731810, 2025). "Specifically, studies have found that Ligilactobacillus and Anaeroplasma correlate positively with psoriasis-associated cytokines IL-6, IL-17A, IL-22, and IL-23, while Rikenella, Alistipes, and Mucispirillum are negatively correlated." (PMID 40161116, 2025). "This was associated with an increased ability of the reconstituted macrophages to produce IL-6, confirming that Smad3-deficient macrophages are indeed proinflammatory in the context of psoriasis." (PMID 40067393, 2025). "These core components and core targets can be better molecular docking, and Mendelian randomization analysis showed that there is a causal relationship between the reduced level of IL-6 and the increased risk of psoriasis." (PMID 40898481, 2025). "The risk of MASLD in moderate-to-severe psoriasis is primarily linked to the inflammatory process, which induces pro-inflammatory cytokines such as interleukin (IL)-6, tumor necrosis factor (TNF)-α, and leptin." (PMID 40004904, 2025). "Several studies have also shown an association between elevated IL-6 levels and the severity of psoriasis." (PMID 39200092, 2024). "Elevated levels of inflammatory cytokines such as TNF-α and IL-6 have been linked to reduced sleep in psoriasis." (PMID 39188726, 2024). "The production of psoriasis-development-associated cytokines, such as IL-1, IL-6, IL-17, IL-23, and nuclear factor kappa B (NF-κB), are downregulated by PF-EO treatment in the serum of an IMQ-induced mouse." (PMID 38791435, 2024). "In psoriasis patients with H. pylori infections, the Psoriasis Area and Severity Index (PASI) scores were higher, so were the mucosal levels of psoriasis-associated cytokines IL-1β, IL-6, IL-8, and TNF-α." (PMID 38347543, 2024). "Psoriasis results from overactivity of cytokines such as IL-6, IL-17, and IL-23, which causes keratinocyte hyperproliferation." (PMID 39335596, 2024). "An experimental study in a mouse model of imiquimod-induced psoriasis concluded that treatment with an inflammasome blocker caused reduced expression of pNF-kB, pSTAT-3, IL-6, and TNFα." (PMID 38965465, 2024). "For example, there was evidence that IL-6 rs2069840 polymorphism presented in patients with psoriasis was associated with increased EAT volume." (PMID 39200903, 2024). "This is also true for the release of cytokines like IL-17, IL-6, and IL-1β, which are closely linked to the development of psoriasis." (PMID 39296901, 2024). "Increased levels of inflammatory cytokines such as TNF-α and IL-6 are associated with reduced sleep duration in psoriasis patients." (PMID 39188726, 2024). "We established an in vitro model of psoriasis, based on an inflammation-associated keratinocyte proliferation model, and used macrophages and keratinocytes treated with LPS, IL-6, or IFN-γ to evaluate the effect of CMX." (PMID 36838711, 2023). "IL-6 is known to be a cytokine that is essential for initial differentiation of Th17 cells, a key population of cells associated with pathogenesis in psoriasis." (PMID 36982669, 2023). "Their proliferation is responsible for the phenotypic outcome of psoriasis and is associated with the IL-22 and IL-6/STAT3 pathways." (PMID 37958980, 2023). "Other loci related to the IL-17/IL-23 axis and involved in psoriasis susceptibility correspond to genes coding for IL-6, with a protective effect, or KLF4 genes." (PMID 37628670, 2023).
psoriasis (continued). "In particular, genetic polymorphisms for interleukin (IL)-1, IL-6, and tumor necrosis factor-α have been linked to both psoriasis and periodontal disease, respectively." (PMID 37046012, 2023). "It is well established that cytokines TNF‐α, IL‐1β, IL‐6, and IL‐17 are involved in tissue inflammation, especially in skin inflammation associated with psoriasis, and can interact with immune cells to exert proinflammatory effects." (PMID 37506136, 2023). "Psoriasis is caused primarily by pro-inflammatory cytokines such as interleukin 6 (IL-6), interleukin 1β (IL-1β), and tumor necrosis factor-alpha (TNF-α) from stressed keratin-forming cells." (PMID 37643205, 2023). "Psoriasis, which is characterized by hyper-proliferative keratinocytes and auto-reactive immune cells, was associated with low serum levels of H2S and high IL-6, IL-8, and TNFα." (PMID 36768979, 2023). "Psoriasis is an inflammatory condition that is associated with excessive secretion of proinflammatory cytokines (IL-2, IL-6, IL-8, IL-12, IL-19, IL-22, IL-23, IFN-γ and TNF-α) into blood as well as dermal tissue." (PMID 37266425, 2023). "Cytokines (e.g., IL-6, -19, -20, -22 and -24) have been associated with the psoriasis pathogenesis and can induce the activation of STAT3." (PMID 37998534, 2023). "While numerous pro-atherogenic cytokines are elevated in psoriasis, it is worth noting that IL-6, IL-17, IFN-γ and TNF-α assume a prominent role in causing endothelial dysfunction and the development of atherosclerosis." (PMID 37998534, 2023). "IL-6 has been associated with the pathogenesis of psoriasis and increased levels of this cytokine in the skin and serum is a characteristic of this disease." (PMID 37373278, 2023). "IL-6 has long been associated with the pathogenesis of psoriasis and is elevated in the serum and skin of patients with psoriasis." (PMID 36982669, 2023). "Previous studies have shown that LGALS7 expression is reduced in lesional skin from patients with psoriasis and that this reduction is associated with keratinocyte hyperplasia via increased cytokine (IL-6 and IL-8) expression and ERK signaling." (PMID 37805522, 2023). "Given that chronic inflammation is a hallmark of psoriasis, we then perform an RT-PCR assay to determine the mRNA levels of IL-1β, IL-6, and TNF-α." (PMID 35351863, 2022). "Examples are accumulation of granulocytes stimulated by IL-8, IL-17, IL-9 and IL-13; epidermal hyperplasia and psoriasis-like skin lesions due to IL-22; and fever and weight loss in response to IL-6 and IFN-γ." (PMID 34503066, 2021). "It has been observed that epidermal expression of STAT3 in a transgenic mouse, activated by the IFN-γ, IL-6, IL-20, IL-17A, and IL-22 cytokines, causes psoriasis." (PMID 34769005, 2021). "UCB-MNC-sEV treatment significantly reduced the expression of psoriasis-associated molecules, including IL-6 and IL-8, as well as antimicrobial peptides S100A7 and DEFB4, thereby supporting its therapeutic potential for this disease." (PMID 34575956, 2021). "Inflammatory response, positive regulation of NF-қB transcription factor activity, positive regulation of T cell proliferation, regulation of inflammatory response, and IL-6 production was intricately linked to the pathogenesis of psoriasis." (PMID 34168554, 2021). "Obesity and psoriasis have a common pathogenic mechanism involving the fat cells critical for the synthesis of the pro-inflammatory cytokines IL-6 and TNF-α." (PMID 34372872, 2021). "Keratinocyte TNIP1 deficiency sensitizes cells to PAMPs and DAMPs promoting hyperresponsive expression and secretion of cytokine markers (e.g., IL-8 and IL-6) relevant to cases of chronic inflammation, like psoriasis, where TNIP1 deficiency has been reported." (PMID 32377162, 2020). "Taken together, blockade of IL-6 signaling with an anti-IL-6R antibody is a potential therapeutic approach to resolve psoriasis-like dermatitis caused by inhibition of PD-1." (PMID 33060784, 2020).
psoriasis (continued). "We now confirm that induction of S100-alarmins in an imiquimod-induced murine model of psoriasis-like skin inflammation was associated with an increased expression of interleukin (IL)-1α, IL-6, IL-17A, or TNFα." (PMID 33643287, 2020). "Keratinocyte-derived OAS2 can be induced by not only IFNβ, but also psoriasis associated cytokines like IL-17A and IL-6." (PMID 32849499, 2020). "Psoriasis-like HPKs showed an increased protein expression of the psoriasis-associated pro-inflammatory cytokine IL-6 and the chemokine IL-8." (PMID 32316273, 2020). "Psoriatic arthritis is chronic inflammatory arthritis that is associated with psoriasis and thus somewhat related to the successful indication for IL6, a cytokine with a wide variety of biological functions." (PMID 30736745, 2019). "Cytokines such as tumor necrosis factor alpha (TNFα) and interleukin 6 (IL-6) are directly implicated in the pathology of psoriasis and are targets for some highly effective treatments." (PMID 30703100, 2019). "Elevated levels of TNF-α, a key player of angiogenesis, and other cytokines including IL-1 and IL-6 in psoriasis are associated with type 2 diabetes." (PMID 29904118, 2018). "We added psoriasis-associated cytokines of Th1 (TNFα, IL-6, and IL-1α) and Th17 (IL-17 and IL-22) origin to N/TERT1 HEEs during the last three days of the air-liquid interphase culture." (PMID 28928444, 2017). "Cytokines including IL-6, -19, -20, -22 and -24 have been implicated in the pathogenesis of psoriasis and can initiate the activation of STAT3." (PMID 29232931, 2017). "The IL-17A concentration was higher in moderate to severe psoriasis, while higher IL-6 levels were associated with joint involvement and sporadic form of psoriasis." (PMID 28790368, 2017). "IL-6 is associated with various cutaneous inflammatory disorders, such as atopic dermatitis, psoriasis, and photoaging." (PMID 28994699, 2017). "Increased levels of IL-6 have been associated with a number of skin pathologies, such as psoriasis, atopic dermatitis and microbial skin infections." (PMID 28143523, 2017). "IL-6 is one of the cytokines that is induced in various cell types and is associated with cutaneous inflammatory disorders, such as psoriasis and photoaging." (PMID 27626393, 2016). "Psoriasis is associated with activation of an IL-22 and IL-6/STAT3 pathway, which contributes to keratinocyte hyperproliferation and failure to exit the cell cycle with the inability to fully mature into corneocytes." (PMID 27537526, 2016). "The clinical efficacy of anti-TNF-α drugs in patients with psoriasis and/or joint disease was associated with (i) reduction of IL-6 and IL-22 in sera; (ii) increments of regulatory T cells; (iii) reduction of cutaneous homing receptor expressing T cells." (PMID 25136144, 2014). "Both TNFα and the IL-23/Th17 axis are strongly implicated in the pathogenesis of psoriasis, while IL-6 has recently been shown to be important in preventing immune suppression by regulatory T cells." (PMID 24665164, 2014). "In an Egyptian population (46 cases and 96 controls), an association was established between psoriasis and SNPs in IL6 (CC genotype in rs1800795) and IL10 (GG genotype in rs1800896)." (PMID 24069534, 2013). "Overexpression of IL-6 and IL-12 has been implicated in the pathology of psoriasis in addition to several other autoimmune and chronic inflammatory diseases." (PMID 23226485, 2012). "Dysregulation of IL-6 is closely associated with many diseases, including psoriasis." (PMID 40906403, 2025). "Additionally, several pro‐inflammatory cytokines such as TNF‐α, IL‐6, IL‐23 and IL‐17 are implicated in the onset and pathogenesis of both psoriasis and periapical lesions." (PMID 40105908, 2025). "Compared with monoculture, psoriasis-derived mesenchymal stromal cells (PsO-MSCs) co-cultured with healthy donor MSCs (H-MSCs) secreted substantially lower levels of hallmark psoriatic pro-inflammatory cytokines (IL-6, IL-12, IL-13, IL-17A, TNF, and G-CSF)." (PMID 41226338, 2025).
psoriasis (continued). "In order to explore the relationship between PGGT1B deficiency and inflammation in psoriasis, we measured the mRNA and cytokine expressions of inflammatory factors IL-1β, IL-6, TNF-α, IL-17A, and IL-10 in the most serious stage of skin injury in mice using Luminex and qRT-PCR." (PMID 40430037, 2025). "It is recognized that some cytokines, particularly TNF-α and IL-6 which are frequently seen in psoriasis and OSA could induce sleep and may cause EDS." (PMID 40232659, 2025). "In this study, in order to explore the relationship between PGGT1B deficiency and inflammation in psoriasis, we also detected the mRNA and cytokine expressions of inflammatory factors IL-1β, IL-6, TNF-α, IL-17A, and IL-10 in the most serious stage of skin injury in mice." (PMID 40430037, 2025). "It was found that certain polymorphisms in the IL-6 gene (e.g., −174 G > C) may increase the risk of developing psoriasis, which is consistent with our MR results." (PMID 40898481, 2025). "In conclusion, our findings highlight IL-6 as a promising biomarker that integrates residual inflammation and dysfunctional visceral adiposity, two central drivers of metabolic and cardiovascular risk in psoriasis." (PMID 41472738, 2025). "IL-6 has also been associated with psoriasis over the past two decades, but its effect remains controversial as it may have both positive and negative impacts." (PMID 40343299, 2025). "In people with psoriasis, serum IL-6 levels may be associated with skin and joint disease severity, as IL-6 triggers synovial inflammation and hyperplasia." (PMID 39429270, 2024). "The pathway causing inflammation from psoriasis begins with genetic predisposition and/or a triggering environment factor that damages keratinocyte leading to release of interleukin 1, interleukin 6 and tumor necrosis factor α and also leading to the activation of dendritic cells." (PMID 39274352, 2024). "However, it is believed to be linked to chronic systemic inflammation associated with psoriasis, as well as the release of pro-inflammatory cytokines and adipocytokines from adipose tissue, such as Th17-related cytokines (IL-17, IL-6, and IL-8)." (PMID 39200903, 2024). "In this context, an increased transcript level of pro-inflammatory factors such as IL-6 is the essential hallmark of the disease in addition to further described cytokines important in psoriasis pathogenesis such as TNF-alpha, IL-22 and IL-17." (PMID 37707681, 2024). "Interleukin 6 has been previously implicated in the development of psoriasis." (PMID 38672088, 2024). "K14/Gpx4 mice also developed signs of psoriasis-associated systemic inflammation — elevated serum proinflammatory cytokines (e.g., IL-6), an increase of splenic CD4+ and CD8+ T cells, CD4+ T cell infiltration of the hind-paw synovium, neutrophilic infiltration of the liver and the lungs." (PMID 39570671, 2024). "Moreover, mediators secreted by γδ T cells activate KCs to produce multiple psoriasis-associated mediators, including NF-α, IL-6, CXCL9, CXCL10, and AMPs." (PMID 38642273, 2024). "In psoriasis, uncontrolled keratinocyte proliferation is associated with activation of the mTOR pathway and involves different Th-1, Th-17, and Th-22 immune cells, and their effector cytokines (e.g., IL-1β, IL-6, IL-17A, TNF-α) that act on keratinocytes." (PMID 37371141, 2023). "However, a dysregulated and persistent IL‐6 production is linked with autoimmune skin diseases such as psoriasis and systemic lupus erythematosus." (PMID 37275420, 2023). "In this work, we predict that IL-6-mediated inflammation in psoriasis could be involved in variant TLR4 genotypes." (PMID 36382932, 2022). "In conclusion, the PSORS1C3, CARD14 and TLR4 polymorphisms and haplotypes may be correlated with risk of suffering psoriasis and the IL-6-mediated chronic inflammation in psoriasis could be partially regulated by the TLR4 functional variant." (PMID 36382932, 2022).